FOXE1 (forkhead box E1)
Diseases named in the same sentence as FOXE1 in open-access papers (continued):
Sharing a sentence is not in itself a finding about the gene and the disease.
thyroid cancer (continued). "Accordingly, in the present study we analyzed FOXE1 expression levels in different thyroid cancer cell lines and looked for potential correlations with the genotypes of SNPs rs965513 and rs1867277 and with the length polymorphism rs71369530." (PMID 31846430, 2020). "IHC analysis demonstrates that the solid structures observed by H&E staining in FOXE1+/+ thyroid cancers are composed of PAX8- and TG-positive cell nests distributed throughout the gland." (PMID 33375029, 2020). "Given the established role of FOXE1 in the survival of developing thyroid follicular cells, we also measured apoptosis in thyroid cancers by cleaved caspase-3 staining." (PMID 33375029, 2020). "In the present study, we characterized FOXE1 expression levels in a panel of thyroid cancer cell lines and analyzed the potential role of FOXE1 in the regulation of EMT." (PMID 31846430, 2020). "To further explore the implications of FOXE1 in thyroid cancer, we examined for correlations with aggressive clinical features." (PMID 31846430, 2020). "Located in 9q22.3 and close to the forkhead box E1 (FOXE1) gene, rs965513 conferred an increased risk for thyroid cancer and was named ‘papillary thyroid carcinoma susceptibility candidate 2’ (PTCSC2) gene." (PMID 33218058, 2020). "We therefore analyzed cell migration in the panel of thyroid cancer cell lines in relation to FOXE1 expression and SNP genotype." (PMID 31846430, 2020). "In conclusion, we have identified ZEB1 as a bona fide target of FOXE1 in thyroid cancer cells, which provides new insights into the role of FOXE1 in regulating cell migration and invasion in thyroid cancer." (PMID 31846430, 2020). "Lastly, we studied the mechanism by which FOXE1 controls ZEB1 in thyroid cancer cell lines and demonstrated the involvement of ZEB1 in the regulation of EMT in thyroid cancer cells." (PMID 31846430, 2020). "Here, we show that decreased FOXE1 levels exert pleiotropic effects on thyroid cancer phenotype in vivo." (PMID 33375029, 2020). "Nevertheless, silencing of FOXE1 expression resulted in impaired thyroid cancer cell migration and invasion, and the opposite was observed after FOXE1 overexpression." (PMID 31846430, 2020). "In the context of thyroid carcinoma, several studies have focused on relating FOXE1 expression and localization in cancer cells to tumor development." (PMID 31846430, 2020). "Recent studies have shown that FOXE1 regulates cell proliferation and migration by activating the Wnt/β-catenin pathway in thyroid carcinoma cells." (PMID 33008304, 2020). "Liu reported that the distribution of rs944289 in FOXE1 in thyroid cancer patients and health population was different." (PMID 29788924, 2018). "To note, both SNPs are located in a high linkage disequilibrium (LD) region, which also harbors the rs1867277 (−283G>A FOXE1) SNPs that have been reported as functional in thyroid cancer." (PMID 28928994, 2017). "It is in linkage disequilibrium (LD) with rs965513, which has been associated with thyroid cancer and TSH levels and is in weak LD with rs1867277, which has been associated with thyroid cancer and shown to affect FOXE1 transcription." (PMID 22493691, 2012). "We performed a candidate gene association study in thyroid cancer, showing that FOXE1, formerly called TTF2 (Thyroid Transcription Factor 2), exhibits the strongest association with PTC susceptibility." (PMID 19730683, 2009). "Genes related to thyroid cancer development are involved in DNA repair, ATM (ataxia–telangiectasia mutated) signaling, RET (receptor tyrosine kinase) signaling, and the regulation of thyroid activity (FOXE1, NKX2-1, TSHR)." (PMID 40361383, 2025). "However, a few authors have investigated FOXE1 expression and its epigenetic regulation in thyroid cancer." (PMID 39588344, 2024). "We investigated whether FOXE1 affects the migration and invasion capability of thyroid cancer cells." (PMID 31846430, 2020).
thyroid cancer (continued). "Follicle-like structures were counted in seven fields for each of the six analyzed thyroids for each genotype, confirming that such structures are significantly more represented in thyroid cancers of BRAF FOXE1+/− mice with respect to that of BRAF FOXE1+/+ mice." (PMID 33375029, 2020). "Recent genome-wide association studies (GWAS) and hypothesis driven candidate gene approaches had determined that the FOXE1 genetic variant is downstream of the TSH-cAMP pathway, and is a suspected risk factor for follicular-cell-derived thyroid cancer." (PMID 31937295, 2020). "Increasing evidence from genetic studies associates FOXE1 with PTC, implicating it as a susceptibility gene in thyroid cancer; however, its involvement in the initiation and progression of these tumors is unknown." (PMID 31846430, 2020). "In addition, FOXE1 depletion significantly suppressed the invasion of K1 thyroid cancer cells in Transwell assays with Matrigel." (PMID 31846430, 2020). "Given the potentially crucial role of ZEB1 in EMT, we hypothesized that FOXE1 may regulate the EMT process in thyroid cancer cells, at least partly, by targeting ZEB1." (PMID 31846430, 2020). "In our correlation studies, however, we failed to observe an association between FOXE1 levels and the risk [A] allele of rs965513 or of rs1867277 in the thyroid cancer cell lines analyzed." (PMID 31846430, 2020). "To test whether FOXE1 regulates ZEB1 abundance in human thyroid cancer cells, we silenced its expression in K1 cells, which exhibited the greatest migration and invasion ability of all the PTC lines analyzed." (PMID 31846430, 2020). "At present, many studies have found that FOXE1 gene played a role in skin squamous cell carcinoma, leukemia, pancreatic cancer, breast cancer, thyroid cancer and head squamous cell carcinoma and other tumors, which indicated that the research on FOXE1 was important." (PMID 29788924, 2018). "Three SNPs at two loci were associated with two non-clefting traits, i.e. the FOXE1 locus with thyroid cancer, and the chromosome 3p11 locus with ocular axial length, a quantitative measure for myopia." (PMID 28087736, 2017). "We reasoned that FOXE1 role in thyroid cancer might be explained by discovering its interacting partners and cognate transcriptional pathways." (PMID 27852061, 2016). "The influence of FOXE1 on thyroid cancer has been investigated by Rihab Kallel." (PMID 27191655, 2016). "Considering these data, we hypothesised that increased FOXE1 expression in thyroid carcinomas could be related to a motile advantage of malignant thyroid cells, which would be enhanced by the presence of the rs1867277 A risk predisposing allele." (PMID 19730683, 2009). "For instance, a meta-analysis identified 19 SNPs as significantly associated with thyroid cancer susceptibility, out of which strong associations were identified for 7 SNPs: POU5F1B rs6983267, FOXE1 rs966423, TERT rs2736100, NKX2-1 rs944289, FOXE1 rs1867277, FOXE1 rs2439302, and RET rs1799939." (PMID 39859471, 2025). "Furthermore, TG, FOXE1, and DUOX2 were also shown to be associated with thyroid cancer." (PMID 34209805, 2021). "In addition, we failed to observe any correlation between the FOXE1 poly-A variant and the expression levels of FOXE1 in the thyroid cancer cell lines analyzed (data not shown)." (PMID 31846430, 2020). "Several other polymorphisms along the FOXE1 gene, or in its genomic region, have been associated with both increased susceptibility to PTC and more aggressive tumors in different case-control studies, including an investigation on Chernobyl accident-derived thyroid carcinoma." (PMID 33375029, 2020). "Interestingly, a large body of research indicates a considerable impact of FOXE1 in thyroid cancer." (PMID 30360388, 2018).
thyroid cancer (continued). "FOXE1 or thyroid transcription factor 2 (TTF-2) belongs to the ‘forkhead’ gene family and is involved in promoting the migration process or in repressing differentiation of the thyroid follicular cells until migration has occurred and has been associated with thyroid cancer." (PMID 23251661, 2012). "Therefore, we propose that FOXE1 is acting as an LPG related to thyroid cancer, which is in agreement with the increasing evidence of forkhead box (Fox) proteins having a crucial role in the development and progression of cancer, and their emerging role as potential biomarkers." (PMID 19730683, 2009). "Another such example is lncRNA PTCSC2 which interacts with MYH9 and, thus, reverses MYH9-mediaed inhibition of activities of a bidirectional promoter shared by FOXE1 and PTCSC2 in thyroid cancer." (PMID 37072811, 2023). "In thyroid cancer, lncRNA PTCSC2 has been confirmed to interact with MYH9 to regulate FOXE1 expression." (PMID 35541917, 2022). "Both BRAF FOXE1+/+ and BRAF FOXE1+/− mice instead developed thyroid cancers, which show different morphologies." (PMID 33375029, 2020). "Collectively, miR‐524‐5p targeting on FOXE1 and ITGA3 prevents thyroid cancer progression through different pathways including cell cycling and autophagy." (PMID 30941771, 2019). "In thyroid cancer, there is no consensus on the expression of FOXE1, which has either been upregulated, downregulated, or had similar expression patterns in tumor and non-tumor samples." (PMID 39588344, 2024). "FOXE1 regulates the transcription of thyroglobulin (TG), thyroperoxidase (TPO), NKX2.1, PAX8, Sodium/Iodine Symporter (NIS), and DUOX2, genes required for hormone synthesis, and also regulates PDGFA and ZEB1 in thyroid cancer." (PMID 39588344, 2024). "Therefore, the study of additional cases of malignant struma ovarii, thyroid cancer and cleft palate will help to better understand the relevance of AXIN1 and FOXE1 in thyroid ectopy and malignancy." (PMID 38396644, 2024). "Besides that, transcriptional FOXE1 expression was significantly downregulated in poorly differentiated thyroid carcinoma and absent in anaplastic thyroid cancer." (PMID 39588344, 2024). "Thus, it is likely to the case that the interaction between ETS and certain transcription activators, such as FOXE1, play an important role in TERT activation in thyroid cancer cells while YK-4-279 inhibits TERT expression by disrupting ETS factors’ interaction." (PMID 34221969, 2021). "Given that FOXE1 expression induces both CCL2 and CSF1, together with other chemoattractants, in thyroid cells in vitro, we asked if FOXE1 could modulate the oncogenic induction of chemokines and hence the infiltration of thyroid cancer by TAMs in vivo." (PMID 34299284, 2021). "Our results highlight a FOXE1 function never described before, which goes beyond the regulation of thyroid-specific molecules and reveals a novel pathway of modulation of macrophage infiltration in the thyroid cancer microenvironment." (PMID 34299284, 2021). "In thyroid cancer, phosphorylation and activation of ETS factor ELK1 by BRAF/MAPK pathway were necessary for thyroid-specific FOXE1 recruitment to TERT promoter via direct ELK1–FOXE1 interaction and this recruitment was independent from cis-acting mutations of TERT promoter." (PMID 34221969, 2021). "Although FOXE1 levels positively correlated with migration rate in some cell lines, we could not establish a correlation between FOXE1 expression and the ability of thyroid cancer cell lines to migrate and invade." (PMID 31846430, 2020). "However, the possibility that changes in FOXE1 expression modulate thyroid cancer development has not been investigated." (PMID 33375029, 2020). "In addition, several studies have focused on assessing whether a correlation exists between SNPs/haplotypes and FOXE1 expression in thyroid carcinomas, but the results are not always in agreement." (PMID 38396644, 2024).
thyroid cancer (continued). "We also examined the expression of ZEB1 in a panel of human thyroid cancer cell lines, but we could not establish a clear correlation between ZEB1 and FOXE1 expression." (PMID 31846430, 2020).
papillary thyroid carcinoma (20 papers, 2009 to 2024). "In the past few years, these polymorphisms (rs965513, rs944289 and rs1867277) in the Forkhead factor E1(FOXE1) region and differentiated thyroid cancer (DTC) risk had been independently researched by subsequent studies." (PMID 29788924, 2018). "The llelic, genotypic and phenotypic analyses strongly suggested that the length of the alanine stretch in FOXE1 modulates genetic susceptibility to papillary thyroid cancer." (PMID 27191655, 2016). "Several recent GWAS and a parallel candidate gene study reported consistent associations between variants in the FOXE1 region (rs965513, rs1867277, rs7850258) and risk of papillary thyroid cancer and/or primary hypothyroidism." (PMID 23520464, 2013). "As reflected in the Gene Expression Omnibus database, FOXE1 variations have been associated with susceptibility to several types of cancer, including papillary thyroid cancer." (PMID 23675434, 2013). "Significant polymorphisms in the FOXE1 locus when comparing Papillary Thyroid Cancer patients against controls in the Spanish population (Phase I)." (PMID 19730683, 2009). "In the present work, by means of a two-step candidate-gene association study, we have identified FOXE1 as a low penetrance gene (LPG) associated with papillary thyroid cancer (PTC)." (PMID 19730683, 2009). "SNPs in an LD block spanning the entire FOXE1 gene showed the strongest evidence of association with papillary thyroid carcinoma susceptibility." (PMID 19730683, 2009). "Combined association results for FOXE1 promoter variant rs1867277 (c.−283 G>A) in Papillary Thyroid Carcinoma patients against controls." (PMID 19730683, 2009). "The FOXE1 gene is a candidate gene associated with thyroid papillary carcinoma found by GWAS." (PMID 29788924, 2018). "Therefore, this meta-analysis was conducted to make this discrepancy clear and to create a comprehensive picture of the association between common variants on FOXE1 and differentiated thyroid cancer." (PMID 29788924, 2018). "Moreover, FOXE1 variations have been associated with susceptibility to several types of cancer, including papillary thyroid cancer." (PMID 23675434, 2013). "In this study, focused on genes carefully selected by their biological relation with the disease, and using more than 1,000 cases and 1,000 representative controls from two independent Caucasian populations, we demonstrate that FOXE1 is associated with Papillary Thyroid Cancer susceptibility." (PMID 19730683, 2009). "MYH9 inhibits the activity of the bidirectional promoter shared by Forkhead Box E1 (FOXE1) and the lncRNA gene papillary thyroid carcinoma susceptibility candidate 2 (PTCSC2)." (PMID 39273383, 2024). "Mechanistically, it has been reported that miRNA-524-5p inhibits the progression of papillary thyroid carcinoma cells by targeting FOXE1 and ITGA3 in cell autophagy and cycling pathways." (PMID 35488119, 2022). "MiR-524-5p, a downregulated miRNA in papillary thyroid carcinoma, was shown to promote autophagy and inhibit cell viability, invasion, migration and apoptosis by targeting ITGA3 and FOXE1 in papillary thyroid cancer." (PMID 33390839, 2021). "The transcription factor Forkhead box E1 (FOXE1) is a key player in thyroid development and function and has been identified by genome-wide association studies as a susceptibility gene for papillary thyroid cancer." (PMID 33375029, 2020). "The expression of miR‐524‐5p was decreased in the papillary thyroid cancer tissues and cell lines, while forkhead box E1 (FOXE1) and ITGA3 were increased." (PMID 30941771, 2019). "Haplotype analysis of the FOXE1 locus in Spanish classic Papillary Thyroid Carcinoma cases versus controls." (PMID 19730683, 2009). "Promoter hypermethylation downregulates FOXE1 expression in different tumor types; nevertheless, its expression and relationship with methylation status in differentiated thyroid cancer (DTC) remain unclear." (PMID 39588344, 2024).
papillary thyroid carcinoma (continued). "One study analyzing the FOXE1 expression in papillary thyroid carcinoma showed increased number of macrophages in the periphery of tumor tissue, which may also indicate that FOXE1 might affect macrophage activity in tissue remodeling processes." (PMID 33917041, 2021). "The Authors generated wild-type and mutant constructs of FOXE1 and performed functional studies on rat normal thyroid cells and human papillary thyroid carcinoma cell line, supporting a role of FOXE1 in tumorigenesis, since mutant FOXE1 promoted cell proliferation and migration." (PMID 33946592, 2021). "miR‐524‐5p could inhibit papillary thyroid cancer cell viability, migration, invasion, and apoptosis through targeting FOXE1 and ITGA3." (PMID 30941771, 2019). "A correlation study between Forkhead box E1 (FOXE1) gene variants rs894673, rs1867277, and rs3758249, and histopathological features of TC, suggested that FOXE1 variations generate a higher risk for poor histopathological features in papillary thyroid carcinoma." (PMID 29178884, 2017). "In the clinical case, expression of miR‐524‐5p, FOXE1, and ITGA3 were significantly correlated with papillary thyroid cancer development and progression." (PMID 30941771, 2019).